LEP (leptin)
Diseases named in the same sentence as LEP in open-access papers (continued):
Sharing a sentence is not in itself a finding about the gene and the disease.
Obesity (continued). "It was late onset, and a relatively modest increase in body weight compared to some other genetic mouse models of obesity, for example the leptin deficient ob/ob mouse." (PMID 29227996, 2017). "Leptin levels are closely related to, or even reflecting, body fat mass and obesity associated metabolic parameters in both mice and humans." (PMID 28542631, 2017). "Selective leptin resistance, obstructive sleep apnea syndrome, hyperinsulinemia and low ghrelin levels are possible mechanisms underlying sympathetic activation in obesity." (PMID 28966594, 2017). "Yet, regions marked by obesity and type 2 diabetes SNPs were associated with numerous significant regulatory impacts on genes within the glucose-insulin and leptin signaling pathways." (PMID 29081791, 2017). "A number of studies have demonstrated that obesity is associated with increased plasma leptin level." (PMID 28645299, 2017). "Decreased leptin signaling in the presence of high titers of circulating leptin, or leptin insensitivity/resistance, is often implicated as contributing to human obesity." (PMID 28443063, 2017). "As expected, despite a standard postnatal diet the adult male offspring developed obesity associated with increased caloric intake, as well as reduced insulin sensitivity, increased plasma leptin and triglyceride levels, and higher systolic blood pressure." (PMID 28717143, 2017). "Obesity is a significant risk factor for pancreatic cancer, harboring a chronic inflammatory condition characterized by dysregulation of the adipokines, leptin and adiponectin, that in turn alter oncogenic signaling pathways." (PMID 29156726, 2017). "Low grade inflammation and changes in microbiota are associated with obesity and have been discussed as possible causes, along with insulin-like growth factor-1 and leptin." (PMID 28804436, 2017). "In mice, mutation of both leptin and the leptin receptor is associated with obesity and disturbed glucose homeostasis." (PMID 28441764, 2017). "Over the past few decades, two obesity-related gene polymorphisms have been most commonly reported: LEP G2548A rs7799039, and LEPR Q223R rs1137101." (PMID 28938640, 2017). "Leptin is an adipocyte-derived hormone that is often elevated in obesity and has been shown to contribute to obesity-associated increases in blood pressure." (PMID 28093508, 2017). "Mice having a homozygous mutation of the leptin gene show a phenotype of hyperphagia, extreme obesity, diabetes, neuroendocrine abnormalities, and infertility." (PMID 30970978, 2017). "There are a limited number of studies analyzing PLIN gene polymorphisms and adikopine levels in obesity and leptin was examined in them." (PMID 28274232, 2017). "In contrast to leptin, adiponectin, a 244-residue protein produced primarily by adipocytes, was suggested to be inversely associated with obesity." (PMID 28662701, 2017). "Leptin and adiponectin play an important role in obesity-associated metabolic risk by modulating inflammatory processes and affecting insulin sensitivity." (PMID 28077136, 2017). "Leptin administration is an effective treatment for obesity in mice and humans with genetic leptin deficiency." (PMID 28303116, 2017). "To assess the importance of ARC in β-cell survival under the stressed conditions of type 2 diabetes, we crossed ARC −/− mice with ob/ob mice, a leptin deficient line that exhibits obesity and type 2 diabetes." (PMID 28765602, 2017). "Obesity is a strong risk factor for the development of cardiovascular diseases and is associated with a marked increase in circulating leptin concentration." (PMID 27677429, 2017). "Next, since all the genes at these leptin-increasing loci were found to be expressed in the CNS, we tested if leptin plays a mediation role in genetic predisposition to polygenic obesity." (PMID 29212175, 2017). "Several drugs have been used to directly assess the role of HI in the obesity of rodents with mutations in leptin." (PMID 28466412, 2017).
Obesity (continued). "Leptin is a hormone that is secreted by white adipose tissue to aid in the regulation of obesity by inducing weight loss and homeostasis of bone." (PMID 28183304, 2017). "Adiponectin and leptin are two adipocytokines or adipokines that have been studied extensively due to their association with insulin resistance, obesity and cardiovascular (CV) risk." (PMID 28068986, 2017). "In order to evaluate bioactive leptin as a biomarker for leptin gene mutations and insulin resistance, we have selected 70 probands with early-onset severe obesity." (PMID 28542631, 2017). "In 1997 came the first report that two young cousins with severe early onset obesity harboured mutations in the gene encoding leptin (LEP), confirming that this system was relevant across mammalian species." (PMID 28013339, 2017). "The most severe form of obesity in mice and humans results from a deficiency in the genes encoding leptin (LEP) or the leptin-receptor (LEPR)." (PMID 28592656, 2017). "In line with previous evidence from other authors, an association between obesity and higher serum concentrations of leptin, MDA, CRP and glucose was corroborated in our study." (PMID 28555008, 2017). "Obesity is associated with increased plasma leptin concentrations compared to normal weight individuals." (PMID 28357137, 2017). "Obesity is also characterized by sustained elevated circulating levels of the adipokine leptin, which is positively associated with body fat mass." (PMID 29186929, 2017). "Taken together, our data suggest that leptin prevent the obesity-associated inflammatory state and the increased oxidative stress in leptin-deficient ob/ob mice." (PMID 28584304, 2017). "The expression of NILCO molecules (Notch, IL-1, and leptin crosstalk outcome) and the association with obesity were investigated in types I and II endometrial cancer (EmCa)." (PMID 28659656, 2017). "Leptin has received significant attention as key mediator of developmental programming with alterations in the leptin in early life linked to an increased risk for obesity and metabolic dysregulation in later life." (PMID 28993758, 2017). "Obesity is an additional risk factor of psoriasis possibly due to shared characteristics, such as higher serum levels of leptin and/or VEGF-α and lower levels of adiponectin." (PMID 28708082, 2017). "In the current literature, four mutations in the gene coding for leptin have been reported which lead to leptin deficiency and result in severe obesity." (PMID 29312147, 2017). "While genetic leptin deficiency is rarely a cause of human obesity, leptin resistance is common in obese patients." (PMID 28427343, 2017). "We aimed to evaluate the proportion of bioactive leptin serum levels (compared to immunoreactive leptin) as a biomarker for the screening of leptin gene mutations causing monogenic obesity." (PMID 28542631, 2017). "To date, not less than 50 genes (including leptin, ObR, and mediators of leptin signaling) are related to an increased obesity risk in humans and rodents." (PMID 28270795, 2017). "In another study, the ineffectiveness of Orthosiphon stamineus plant for reducing weight in diet-induced obesity has been linked to the development of leptin resistance in mice." (PMID 29025435, 2017). "Genetic variations in some obesity-related genes have been demonstrated to affect BC risk by the levels and functioning of leptin." (PMID 28938640, 2017). "It is worth mentioning that only a small percentage of obesity cases are caused by mutations in single genes, such as leptin (LEP), leptin receptor (LEPR), and melanocortin 4 receptor (MC4R)." (PMID 28810876, 2017). "Using STR markers flanking the LEP locus at human chromosome 7q31.3-32.1, several groups reported evidence of linkage and/or association between these STRs and obesity-related traits, albeit with inconsistencies." (PMID 28615046, 2017).
Obesity (continued). "There is growing consensus that reduced blood–brain transport of leptin is a contributing factor to leptin insensitivity in the face of high leptin titers caused by obesity [reviewed in Ref." (PMID 28443063, 2017). "A similar but weaker patternwas observed for measures at age 17 where cord leptin was associated withz scores of fat mass, waist circumference, and BMI and with the riskof obesity." (PMID 27841944, 2017). "We concluded that circulating concentrations of adiponectin are positively regulated by leptin and ameliorate obesity-associated oxidative stress and inflammation in mice." (PMID 28584304, 2017). "Endocrine factors regulate AP, and elevated circulating leptin concentrations are a common metabolic disturbance associated with obesity that have been implicated in the pathogenesis of hypertension." (PMID 28093508, 2017). "More recently, increased endoplasmic reticulum stress was also suggested as a mediator of the obesity-associated central leptin resistance." (PMID 28321206, 2017). "Conversely, we want to analyze the allele frequency of published mutations in the leptin gene, known to cause severe obesity when inherited homozygously." (PMID 29101506, 2017). "Such pathways should provide beneficial pharmacological targets, and lead to the development of new generation drugs that can safely and effectively treat overweight and obesity linked to leptin resistance." (PMID 28424580, 2017). "For example, mice with congenital deficiency of leptin (ob/ob mice) exhibit hyperphagia, reduced energy expenditure, obesity, and infertility." (PMID 28357399, 2017). "As an animal model, the ob/ob mouse is commonly used to study the T2DM phenotype and leptin resistance characteristic of obesity and T2DM, particularly when associated with metabolic syndrome." (PMID 28183304, 2017). "On the other hand, protracted HFD, can result, along with severe obesity, in loss of leptin responsiveness that cannot be restored by simply increasing the administered dose, also because of impaired transport across the blood-brain-barrier." (PMID 28804449, 2017). "Herein, to understand the underlying relationship between obesity and brain tumors, we investigated the effect of leptin, alone or in combination with sPLA2-IIA on astrocytoma cell functions." (PMID 28249041, 2017). "Other mechanisms, including hypothalamic inflammation and endoplasmic reticulum (ER) stress, are known to be involved in obesity-associated leptin resistance." (PMID 28912580, 2017). "Obesity was consistently and strongly associated with LEP methylation and that association varied by sex." (PMID 28360946, 2017). "Studies in rodents and humans demonstrated that NK cell cytotoxicity in obesity was associated with higher serum leptin levels." (PMID 28357137, 2017). "The observations that humans and rodents with congenital leptin deficiencies are sterile and that anorexia and obesity delay and accelerate the onset of puberty, respectively, led to the idea that leptin is an important player in reproduction." (PMID 28270795, 2017). "The initial moment of obesity caused important metabolic abnormalities, such aselevated leptin (62.5%) and insulin (40%) levels in the HF group." (PMID 29069204, 2017). "Leptin is an adipokine hormone involved in regulating food intake and energy metabolism and leptin resistance has been associated with obesity and HFD-feeding, resulting in hyperleptinemia, a decreased satiated feeling, and cardiovascular damage." (PMID 29104232, 2017). "Lesion incidence was associated with factors related to obesity, namely percentage body fat, plasma leptin concentration and markers associated with chronic inflammation (TNFα)." (PMID 29166409, 2017). "Here we tested the consequences of therapeutic silencing of Fsp27 using generation 2.0 antisense oligonucleotides (ASOs) in both a dietary [high-fat diet (HFD)] and a genetic (leptin-deficient ob/ob) model of obesity, hepatosteatosis, and insulin resistance." (PMID 27884961, 2017).
Obesity (continued). "In rare cases of obesity due to leptin deficiency, the administration of human recombinant leptin leads to an apparent increase in insulin sensitivity, possibly associated with a rapid weight loss." (PMID 28626772, 2017). "Obesity is characterized with co-existing metabolic disturbances, and of these especially leptin in males and hs-CRP in females associate with impaired skeletal health." (PMID 28640843, 2017). "Genetic association studies have provided insights into the genetics of early-onset obesity, identifying strongly associated genes with large phenotypic effects such as the leptin (LEP) or leptin receptor (LEPR) genes." (PMID 28771179, 2017). "Leptin deficiency inhibits Hedgehog signaling in pericytes to trigger a pericytopathy that promotes both adiposity and obesity-related tissue damage." (PMID 28427343, 2017). "The ob/ob mouse carries a spontaneous mutation in the leptin gene, which results in a leptin deficiency, subsequently leading to hyperphagia, inactivity, obesity, insulin resistance, and hepatic steatosis." (PMID 28736524, 2017). "Altered leptin, adiponectin, and oxidative stress markers have been documented in pregnant women with obesity, and have been associated with adverse perinatal outcomes." (PMID 29283404, 2017). "Yet, they also demonstrate the difficulty in establishing causality between neonatal leptin levels and susceptibility to obesity." (PMID 29190757, 2017). "Obesity is associated with leptin and insulin resistance leading to hyperinsulinemia and hyperleptinemia, which are further linked with excessive body weight, especially central obesity." (PMID 28228098, 2017). "Obesity is associated with increased plasma leptin concentrations of 30–40 ng/mL compared to 5–10 ng/mL plasma leptin concentrations in normal weight individuals." (PMID 28357137, 2017). "Regarding GNB3 rs5443 polymorphism, the likelihood of obesity was linked to the TT genotype which was also associated with increased leptin levels." (PMID 29937877, 2017). "The risk for obesity was two times higher in class I allele carriers; class I allele was associated with increased BMI and WC, and plasma leptin in women." (PMID 28615046, 2017). "In this context, suppressor of cytokine signaling 3 (SOCS3) seems to be a key protein in central leptin resistance because its loss of function in the hypothalamus confers protection to high-fat diet (HFD)-induced obesity." (PMID 28321206, 2017). "Obesity is associated with resistance to the biological effects of both insulin and the satiety hormone leptin." (PMID 28360931, 2017). "Specifically, mounting evidence indicate that several obesity-associated factors such as insulin, leptin, adiponectin or triglycerides can contribute to the development and/or progression of several cancer types, including BCa." (PMID 29113405, 2017). "Animals that lack leptin (ob/ob), or its long receptor, LepRb (db/db), display a phenotype with voracious appetite and obesity, while correcting the deficiency ameliorates the abnormal phenotype." (PMID 27998953, 2017). "Early-onset, extreme obesity due to biologically inactive leptin is a new disease entity characterized by high immunoreactive levels of circulating leptin, but a reduced bioactivity of the hormone caused e.g. by defects in receptor binding." (PMID 28007844, 2017). "Specifically, major players like melanocortin 4 receptor (MC4R), leptin (LEP), and fat mass and obesity-associated gene (FTO) are known key regulators of feed intake/appetite and energy homeostasis." (PMID 28831160, 2017). "Obesity caused changes in several adipogenic genes including leptin, and women with ER+/PR+ tumours that had high leptin expression had a poorer prognosis." (PMID 29104428, 2017). "As extreme obesity due to bioinactive leptin due to poor receptor binding – like in leptin deficiency – is a treatable condition, the diagnosis should be confirmed or excluded in any suspected case as early in life as possible." (PMID 28007844, 2017).
Obesity (continued). "Leptin-deficient ob/ob mice have been studied intensively as a model of obesity and its co-morbidities: ob/ob mice are not only hyperphagic and morbidly obese, but also dysmorphic and prone to various types of tissue damage." (PMID 28427343, 2017). "Leptin or ObR deficiencies not only cause severe obesity but also abnormalities in hematopoiesis, immunity, reproduction, angiogenesis, bone formation, and blood pressure (BP)." (PMID 28270795, 2017). "The disruption on (or resistance to) the action of leptin is a hallmark of obesity, which in turn is a strong risk factor for several diseases including diabetes, cardiovascular disease, and certain types of cancers." (PMID 29268695, 2017). "Accumulating evidence from clinical and animal studies suggests that obesity-associated molecules including leptin, insulin, IGF-1, and adiponectin influence the development of colonic diseases." (PMID 28170448, 2017). "A low birth weight was associated with a higher prevalence of diabetes and obesity, higher leptin levels and leptin to fat mass ratio possibly related to nutrition or the development of leptin resistance and/or higher leptin production by body fat unit." (PMID 28068986, 2017). "These offspring displayed obesity despite lowered energy intake associated with alterations in hypothalamic leptin signalling." (PMID 28092346, 2017). "LEPR has diverse roles in metabolism, appetite and bone formation with obesity linked to both elevated levels of leptin and increased cancer incidence." (PMID 29212170, 2017). "Mainly two adipose tissue mass-dependent adipokines—adiponectin (ADIPO) and leptin—have attracted the attention of scientists as possible mediators of CVD risk associated with obesity." (PMID 28947858, 2017). "AA + GA genotype had a better leptin sensitivity shown by its response in dietary intake and body mass index (BMI) and this explained the protective effect of A allele to obesity." (PMID 28686191, 2017). "Significantly high serum leptin levels were presented in obese subjects compared to a healthy control population suggesting the leptin resistance as the main risk factor to induce obesity." (PMID 28143489, 2017). "High-serum levels of leptin contribute to the inflammatory state of the adipose tissue associated with obesity." (PMID 28894445, 2017). "A decrease or loss of leptin signaling in early postnatal life impairs development of the feeding circuit, and also predisposes individuals to leptin resistance and obesity as adults." (PMID 28533765, 2017). "Studies have demonstrated that serum leptin levels are increased in obesity and have been suggested as a risk factor for CC." (PMID 28819564, 2017). "Previously, it was suggested that leptin and insulin levels, and insulin resistance have different associations with obesity." (PMID 29088261, 2017). "The leptin-deficient ob/ob mouse is widely used to study aspects of obesity and insulin resistance, and has been put forward as a model to study early stages of T2D19." (PMID 28751653, 2017). "The objective of this work was to analyze the expression of AdipoR1 and AdipoR2, modulated by differential concentrations of leptin in an obesity model (10 ng/mL, 100 ng/mL, and 1000 ng/mL) associated with breast cancer in MCF-7 and HCC1937 cell lines." (PMID 29311755, 2017). "There is mounting evidence that early life nutrition is an important determinant for risk of obesity, and modulation of leptin signaling during critical developmental periods can have long-term consequences for adult physiology." (PMID 28533765, 2017). "Hyperleptinemia has been associated with diet-induced obesity, and the development of leptin resistance in obesity has been attributed to the downregulation of cellular responses to leptin." (PMID 29025435, 2017). "Elevated plasma leptin, resulting from increasing adiposity, is associated with the development of hypothalamic leptin resistance, hyperphagia and contributes to obesity." (PMID 28957383, 2017).